DEPDC5 (DEP domain containing 5, GATOR1 subcomplex subunit)
Diseases named in the same sentence as DEPDC5 in open-access papers (continued):
Sharing a sentence is not in itself a finding about the gene and the disease.
liver disease (2 papers, 2014 to 2017). "The genetic factors that play a role in late-stage liver disease remain controversial, although several studies have shown that variants in MICA, DEPDC5, HCP5 and PNPLA3 affect HCC development." (PMID 28928439, 2017). "We have demonstrated that DEPDC5 SNPs, rs1012068 and rs599815were associated with chronic HCV infection and with end-stage liver disease progression." (PMID 25551790, 2014). "However, among chronic HCV-infected Saudi Arabian patients in early- and end-stage liver disease, we did not confirm the association of the risk allele as “G” for DEPDC5 SNP rs1012068 for HCC progression as demonstrated in Japanese population or even for low fibrosis stages." (PMID 25551790, 2014).
lung carcinoma (2 papers, 2025). "We found that not only NPLR2, but also NPRL3 and DEPDC5 are downregulated in these types of lung cancer." (PMID 41469472, 2025).
anaemia (1 paper, 2017). "Depdc5 homozygotes display severe phenotypic defects between 12.5-15.5 dpc, including hypotrophy, anaemia, oedema, and cranial dysmorphology as well as blood and lymphatic vascular defects." (PMID 28974734, 2017). "We found that Depdc5 null mice died during embryogenesis, exhibiting retarded growth, anaemia, eye, liver, cranial and vascular defects." (PMID 28974734, 2017).
Central apnea (1 paper, 2025). Apnea resulting from depression of the respiratory centers in the medulla oblongata. "We therefore expand previous observations of an association between peri‐ictal central apnea and DEPDC5 to other genes involved in the same pathway." (PMID 40971258, 2025). "A recent study highlighted an association between ictal and postictal central apnea (ICA) and pathogenic variants of DEPDC5." (PMID 40971258, 2025).
depression (1 paper, 2022). "Genomic studies have shown that 8% of patients carrying DEPDC5 mutations present with depression." (PMID 35165201, 2022).
duodenal cancer (1 paper, 2024). "K182R inactivates the mTORC1 repressor gene, DEPDC5, thereby driving the progression of duodenal cancer." (PMID 39796732, 2024).
End Stage Liver Disease (1 paper, 2014). Final stage of a liver disease when the liver failure is irreversible and LIVER TRANSPLANTATION is needed. "Altogether, it would be of interest to study DEPDC5 protein function from chronic HCV-infected patients diagnosed with end-stage liver disease to know whether the protein is functional and to investigate its function in the immune system and in hepatocarcinogenesis." (PMID 25551790, 2014).
ganglioglioma (1 paper, 2023). A well differentiated, slow growing neuroepithelial neoplasm composed of neoplastic, mature ganglion cells and neoplastic glial cells. "In patients F43 with FCD type IIB and F70 with ganglioglioma, DEPDC5 and TSC1 were deleted, respectively, together with many other genes through somatic chromosomal deletions." (PMID 36864519, 2023).
glioneuronal tumors (1 paper, 2018). "Identical DEPDC5 and SMO E3 SNP also occurred in all FCD type II samples and the majority of glioneuronal tumors, while the other common SNPs did not occur in all FCD or glioneuronal tumors." (PMID 28833756, 2018).
Hepatic steatosis (1 paper, 2021). Steatosis is a term used to denote lipid accumulation within hepatocytes. "Unexpectedly, the enlarged liver observed in Depdc5-LKO mice cannot be associated with hepatic steatosis, because Depdc5-LKO mice exhibited even slightly reduced liver triglyceride levels compared to LoxP mice." (PMID 34267188, 2021). "Raptor knockdown significantly reversed the ethanol-induced hepatic steatosis caused by Depdc5 deletion." (PMID 34267188, 2021). "After Torin 1 administration, liver-weight-to-body-weight ratios, liver triglyceride levels and serum ALT levels showed dramatic recovery, indicating that sustained hepatic mTORC1 activation is indeed the major cause of hepatic steatosis observed in Depdc5-LKO mice." (PMID 34267188, 2021). "To delineate the molecular mechanisms of Gao-Binge ethanol feeding-induced hepatic steatosis in Depdc5-LKO mice, we assessed the mRNA expression of key genes involved in the main pathways in hepatic lipid metabolism." (PMID 34267188, 2021). "In summary, we demonstrate that hepatocyte-specific Depdc5 deletion hyperactivates mTORC1 signaling and exacerbates ethanol-induced liver steatosis and inflammation." (PMID 34267188, 2021). "Hepatic Depdc5 ablation leads to mild hepatomegaly and liver injury and protects against diet-induced liver steatosis." (PMID 34267188, 2021). "Interestingly, Depdc5-LKO mice exhibited protection from HFD-induced hepatic steatosis." (PMID 34267188, 2021). "Notably, we also observed increased liver-weight-to-body-weight ratios, liver triglyceride contents, and serum ALT levels in Depdc5-LKO mice compared to LoxP mice, indicating Depdc5 deletion-mediated mTORC1 activation worsens the hepatic steatosis induced by ethanol." (PMID 34267188, 2021). "Unexpectedly, we observed an opposite phenotype of lipid metabolism in ethanol-fed Depdc5-LKO mice, which hepatic Depdc5 ablation leads to more severe hepatic steatosis and inflammation in mice exposed to ethanol." (PMID 34267188, 2021). "However, pharmacological inhibition of mTORC1 signaling by Torin 1 treatment (20 mg/kg per day for 5 days) markedly reverses almost all of the ethanol-induced liver abnormalities we observed in Depdc5-LKO mice, including liver steatosis, injury, and inflammation." (PMID 34267188, 2021).
leiomyoma (1 paper, 2023). A well-circumscribed benign smooth muscle neoplasm characterized by the presence of spindle cells with cigar-shaped nuclei, interlacing fascicles, and a whorled pattern. "We have previously reported biallelic loss of DEPDC5 as a secondary event in four clonally related leiomyomas from one patient and in one leiomyoma from another patient." (PMID 35822448, 2023). "In addition to rearrangements of HMGA1, HMGA2, and PLAG1, we identified biallelic loss of DEPDC5 in one leiomyoma with an HMGA2 rearrangement and in another leiomyoma with an HMGA1 rearrangement." (PMID 35822448, 2023).
liver cancer (1 paper, 2018). An epithelial or non-epithelial malignant neoplasm that arises from the liver. "The reasons for DEPDC5 deficiency in liver cancer are as follows; the public data of The Cancer Genome Atlas (TCGA) project identified mutations of DEPDC5 in eight cases (2.1%; missense 7; stop-gain 1) of HCC specimens and worse overall survival of patients with DEPDC5 mutation." (PMID 29311600, 2018).
liver cirrhosis (1 paper, 2014). "This study was conducted to assess the association of DEPDC5 variants with advanced liver cirrhosis and HCC development among chronic HCV-infected patients in Saudi Arabian population." (PMID 25551790, 2014). "Genetic variations in DEPDC5 gene region may influence HCV-associated liver cirrhosis and/or HCC development." (PMID 25551790, 2014).
liver failure (1 paper, 2019). A liver disease characterized by the liver losing or has lost all of its function. "Correspondingly, double knockout of the Tsc1 and Depdc5 genes provokes prominent upregulation of mTORC1, disrupts hepatocellular homeostasis, and subsequently precipitates oxidative injury and subsequent liver failure." (PMID 31754457, 2019).
Phelan-McDermid syndrome (1 paper, 2022). A rare genetic neurodevelopmental disorder characterized by neonatal hypotonia, global developmental delay, normal to accelerated growth, absent to severely delayed speech, and minor dysmorphic features. "Three patients had known genetic etiologies, which included 22q13 deletion syndrome (also known as Phelan-McDermid syndrome), PRRT2 gene mutation and genetic deletion SCX + DEPDC5." (PMID 35496067, 2022).
sarcoma (1 paper, 2021). A usually aggressive malignant neoplasm of the soft tissue or bone. "This is in striking contrast with >250 non-GIST sarcomas where DEPDC5 aberrations are infrequent (~1%)." (PMID 34685669, 2021).
steatosis (1 paper, 2021). Increased lipid within the cytoplasm of cells. "We next examined whether hepatic Depdc5 deficiency contributes to the development of alcohol-induced steatosis in another ALD mouse model, LD 5W model." (PMID 34267188, 2021). "Gao-Binge ethanol feeding-induced liver injury and steatosis were largely normalized in both LoxP and Depdc5-LKO mice by fenofibrate administration." (PMID 34267188, 2021). "A recent study has demonstrated that liver-specific Depdc5 knockouts exhibit many phenotypes similar to Tsc1 knockout mice, such as elevated inflammation and resistance to HFD-induced steatosis." (PMID 34267188, 2021).
tumor (16 papers, 2012 to 2025). "Together, the association of high expression of DEPDC5 with increased tumor-infiltrating CD8+ T cells suggests a regulatory role of DEPDC5 in CD8+ T cells." (PMID 38763950, 2024). "M60 presented additional pathogenic alterations of the DNA damage response (DDR) pathway, and F75 showed pathogenic mutations in multiple tumor suppressor genes, such as DEPDC5 p.W905*, an mTOR inhibitor, and several nuclear DNA effectors." (PMID 33853673, 2021). "Oncogenic E3 ligase CUL3-KLHL22 was observed to mediate K48-linked polyubiquitination of DEPDC5 and target DEPDC5 for degradation under the stimulation of amino acids and promote mTORC1 activation in tumor." (PMID 33004065, 2020). "An additional 12 new protein-coding somatic mutations were identified in the recurrent tumor, including a nonsense mutation in DEPDC5, an inhibitor of mTORC signaling." (PMID 29440180, 2018). "Furthermore, two tumors displayed biallelic loss of DEPDC5 and one tumor harbored a COL4A5–COL4A6 deletion." (PMID 35822448, 2023). "Tumors grew significantly faster in Depdc5tko mice than in Depdc5ncl mice, suggesting a role for DEPDC5 in T cell-mediated anti-tumor immunity." (PMID 38763950, 2024). "NPRL2 (human ortholog of NPR2) and DEPDC5 (human ortholog of IML1) have been reported to function as tumor suppressors." (PMID 23705068, 2013). "Furthermore, our analysis of human cancer sequencing data revealed better overall patient survival and more tumor infiltration by CD8+ T cells in individuals with high expression of DEPDC5, which this study has identified as an anti-ferroptosis gene." (PMID 38763950, 2024). "Searching for our mutated genes in the large pediatric cancer databases PECAN and PedcBioPortal (any tumor) revealed CTNNB1 as the most commonly mutated gene, followed by DEPDC5 (several variants were identified in 12 types of pediatric tumors) in PECAN, and FRMPD1 in PedcBioPortal." (PMID 32432034, 2020). "Overall, DEPDC5 could exhibit tumor suppressor roles in HCC by degrading p62 protein and then elevating cellular ROS levels." (PMID 29311600, 2018). "Together, our study reveals a novel role of DEPDC5 in protecting CD8+ T cells from ROS-induced ferroptosis and uncovers a strategy for promoting anti-tumor immunity by suppressing ferroptosis." (PMID 38763950, 2024). "Using a T cell-specific Depdc5 conditional knockout mouse model, we demonstrate that DEPDC5 protects CD8+ T cells from ferroptosis and is required for CD8+ T cell-mediated anti-tumor immunity." (PMID 38763950, 2024). "Significantly, mice with T cell-specific Depdc5 deletion also had reduced peripheral CD8+ T cells and impaired anti-tumor immunity." (PMID 38763950, 2024). "Together, our study links DEPDC5-mediated mTORC1 signaling with CD8+ T cell protection from ferroptosis, thereby revealing a novel strategy for enhancing anti-tumor immunity via suppression of ferroptosis." (PMID 38763950, 2024). "We found that the expression level of DEPDC5 mRNA in CD8+ T cells was strongly and positively correlated with the extent of CD8+ T cell tumor infiltration." (PMID 38763950, 2024). "DEPDC5 has been suggest to act as a potential tumour suppressor in HCC, and the mRNA expression level of DEPDC5 is downregulated in HCC samples and correlates with poor patient prognosis." (PMID 32752173, 2020). "After subcutaneously injecting the inducible DEPDC5-expressing HCC cells into NOD/SCID mice, we fed them with or without doxycycline in drinking water, and identified delayed tumor growth in the mice administered by doxycycline." (PMID 29311600, 2018). "Their role is underscored by the accumulation of mutations in additional regulators of their activation during the course of this tumor's treatment: MAPK (SPRY3), PI3K (DEPDC5), and WNT (KREMEN2, NET1, GPR124)." (PMID 29440180, 2018). "The mRNA expression level of the DEPDC5 gene was significantly higher in the paired HCC tumor and adjacent nontumor liver tissues." (PMID 36851773, 2023).
tumor (continued). "All five tumors harbored an HMGA2 rearrangement as well, suggesting that DEPDC5 is involved in tumor progression rather than initiation." (PMID 35822448, 2023). "Next, there was significant difference in clinicopathological factors of blood concentration of AFP and PIVKA-II, size of tumor, and grade of portal vein infiltration between the DEPDC5-negative and -positive groups." (PMID 29311600, 2018).
cancer (14 papers, 2012 to 2025). A tumor composed of atypical neoplastic, often pleomorphic cells that invade other tissues. "A more detailed investigation of the roles of DEPDC5 deficiency in cancer cell metabolism will help to define better-targeted therapies." (PMID 29311600, 2018). "To date, somatic mutations in the human IML1/SEA1 homolog, DEPDC5, have been found mutated in cancers and germline mutations have been found in familial autosomal-dominant epilepsy and focal malformations of cortical development." (PMID 25943524, 2015). "There are fewer articles describing the role of NPRL3 and DEPDC5 in cancers, probably because NPRL2 has a higher cancer-associated mutation frequency among GATOR1 components." (PMID 41469472, 2025). "The GATOR1 complex, which consists of DEPDC5, Nprl2 and Nprl3, has GAP activity for RagA/B, and its inactivating mutations in cancers result in mTORC1 hyperactivation." (PMID 29199950, 2017). "Second, we predict that cancers with activating mutations in RHEB, or inactivating mutations in DEPDC5, NPRL2, and NPRL3, will show similar strong response to rapalogs." (PMID 26137524, 2015). "On the other hand, the function of DEPDC5 remains unknown, but is suggested to correlate with several other cancers." (PMID 23132957, 2012). "NPRL2, along with NPRL3 and DEPDC5, forms the GATOR1 complex, an upstream regulator of the mTORС1, the function of which is perturbed in many cancers, particularly those resistant to cisplatin." (PMID 41469472, 2025). "In cancer cells, KLHL22 degrades DEPDC5 and releases inhibition of GATOR1 on mTORC1 in response to amino acid availability." (PMID 36440598, 2022). "In cancer cells and in aging C. elegans, KLHL22 promotes mTORC1 activation by degrading DEPDC5 and releasing inhibition of GATOR1 on mTORC1." (PMID 36440598, 2022).
neurodevelopmental disorder (3 papers, 2017 to 2025). A behavioral and cognitive disorder with onset during the developmental period that involves impaired or aberrant development of intellectual, motor, or social functions. "We then chose two important neurodevelopmental disorder genes, POGZ and DEPDC5, to test this hypothesis." (PMID 33334860, 2021).
neurological disorders (3 papers, 2023 to 2025). "Analysis of these clinical cases further explores the clinical manifestations and pathogenic mechanisms of DEPDC5 mutations across different phenotypes, strengthening our understanding of the relationship between this gene mutation and neurological disorders." (PMID 41141423, 2025).
brain disorder (1 paper, 2022). A disease affecting the brain or part of the brain. "For instance, mimicking DEPDC5 (DEP containing 5 domain) loss-of-function in zebrafish recapitulates critical hallmarks of brain disorders caused by mutations in this gene, such as epileptiform discharges and exacerbated mTOR signaling." (PMID 35875659, 2022). "This study, therefore, opens a yet undiscovered aspect of DEPDC5 biology and related brain disorders." (PMID 35875659, 2022).
infection (1 paper, 2024). The state of being infected such as from the introduction of a foreign agent such as serum, vaccine, antigenic substance or organism. "Through collaboration with physicians at Shanghai Children’s Medical Center, we identified one patient with monoallelic early termination mutation in DEPDC5 (R847X) who displayed reduced blood CD8+ T cell counts compared with a healthy donor and recurrent infection." (PMID 38763950, 2024).
inflammation (1 paper, 2019). Aberrant reaction of the microcirculation characterized by movement of fluid and leukocytes from the blood into extravascular tissues. "We next assessed the association between MICA rs2596542 and DEPDC5 rs1012068 and liver damage (hepatic inflammation and fibrosis)." (PMID 30723271, 2019).
DEPDC5 also shares sentences with these, for which no sentence is quoted: infantile spasms (4 papers); autism spectrum disorder (3); Dravet syndrome (3); cancers of the ovary (2); cardiac arrhythmia (2); colon carcinoma (2); epileptic encephalopathies (2); familial focal epilepsy with variable foci (2); genetic disorder (2); lung adenocarcinoma (2); mental disorder (2); metabolic disease (2); schizophrenia (2); temporal lobe epilepsies (2); 22q11.2 deletion syndrome (1); adult-onset Still disease (1); Angelman syndrome (1); Ataxia (1); bladder cancer (1); bladder urothelial carcinoma (1); Cognitive impairment (1); colonic adenocarcinoma (1); developmental delay (1); Dyskinesia (1); Dystonia (1); early-onset epilepsy (1); fibrosis (1); focal cortical dysplasia type II (1); fragile X syndrome (1); gout (1).
A further 23 diseases each share a sentence with DEPDC5 in 1 paper.